GLI1 (GLI family zinc finger 1)
Diseases named in the same sentence as GLI1 in open-access papers (continued):
Sharing a sentence is not in itself a finding about the gene and the disease.
head and neck squamous cell carcinoma (6 papers, 2016 to 2024). A squamous cell carcinoma that arises from any of the following anatomic sites: lip and oral cavity, nasal cavity, paranasal sinuses, pharynx, larynx, and salivary glands. "Another study demonstrated that elevated GLI1 expression in head and neck squamous cell carcinoma is enhanced by RT, leading to therapy resistance." (PMID 38020914, 2023). "Moreover, radiotherapy elevates GLI1 expression at the intersection of the tumor and stroma in head and neck squamous cell carcinoma, which contributes to the development of stroma-mediated resistance." (PMID 38020914, 2023). "Fertig and colleagues reported higher expression of Gli-1 in HPV negative head and neck squamous cell carcinomas." (PMID 27918595, 2016). "In head and neck squamous cell carcinoma (HNSCC) cells, H3K4ac modulated by HDAC3 is enriched around the transcription start site of EMT related genes such like GLI1 and SMO, co-overexpression of which promotes HNSCC cell invasion and migration ability." (PMID 33262941, 2020).
malignant glioma (6 papers, 2010 to 2021). A grade III or grade IV glioma arising from the central nervous system. "Aberrant activation of sonic hedgehog (SHH)/glioma-associated oncogene homolog 1 (GLI1) pathway plays an important role in the tumorigenicity of malignant glioma cells and resistance to temozolomide (TMZ)." (PMID 28446712, 2017). "Glioma-associated oncogene homolog 1, GLI1, was initially identified as an amplified gene in a human malignant glioma and later, characterized to be a member of the Kruppel family of zinc finger-containing transcription factors." (PMID 21119888, 2010). "Another splice variant of GLI1 was identified in malignant glioma." (PMID 30158435, 2018). "GLI1 (1106 amino acids; MW 117.9kDa) was originally identified as an amplified gene product in a malignant glioma and was the first member described in the human GLI gene family." (PMID 34113570, 2021). "HH signaling was found to regulate dorsal brain tumorigenesis, and GLI1 expression was amplified by more than 50-fold in malignant glioma." (PMID 28899410, 2017). "So, we assessed whether aspirin could be an effective agent in the treatment of malignant glioma via inhibiting the SHH/GLI1 signaling pathway pharmacologically." (PMID 28446712, 2017). "Gli1 was initially found as an amplified gene in a malignant glioma." (PMID 24443799, 2014). "Albeit the human GLI1 was initially isolated from a GBM cell line with GLI1 gene amplification, the incidences of GLI1 amplification in human malignant gliomas were found to be relatively low as reported by studies conducted in the late 1980’s and early 1990’s." (PMID 21119888, 2010).
small cell lung carcinoma (6 papers, 2015 to 2026). Small cell lung cancer (SCLC) is a highly aggressive malignant neoplasm, accounting for 10-15% of lung cancer cases, characterized byrapid growth, and early metastasis. "Arsenic trioxide retards the cancer stem-like transition of small-cell lung cancer cells and regulates stem cell marker expression both in vitro and in vivo through GLI1 repression." (PMID 37149646, 2023). "Thus, Shh–GLI1 pathway inhibitors, such as cyclopamine, have been successfully tested in some cancer types such as medulloblastoma, pancreatic adenocarcinoma, small-cell lung cancer (SCLC), gastric adenocarcinomas, and esophageal cancer." (PMID 26258070, 2015).
Stroke (6 papers, 2014 to 2025). Sudden impairment of blood flow to a part of the brain due to occlusion or rupture of an artery to the brain. "The treatment with BHD increased the levels of Shh, SMO, Ptch1 and Gli1 in the right hippocampus and cortex after stroke." (PMID 40973940, 2025). "Targeting Shh signaling, such as bone marrow stromal cells, BMSCs activate Shh/Gli1 signaling to promote oligodendrocyte production, which in turn treats stroke." (PMID 39364348, 2024). "The upregulation of Shh expression and its transcription factor Gli1 in NPCs improved motor function in stroke mice, indicating its protective role in stroke." (PMID 37047560, 2023). "An increase of Gli1 in the ipsilateral cortex indicated the activation of the Shh pathway early after stroke." (PMID 25341035, 2014). "Gli1 protein level of the nuclear fraction was increased at 9 h after stroke." (PMID 25341035, 2014). "In addition, our present study indicated that resveratrol could inhibit activation of microglia and neuroinflammation via triggering the translocation of Smo and Gli-1 molecules and upregulating the expression levels of Shh, Ptc-1, Smo, and Gli-1 in the acute phase of stroke." (PMID 36836502, 2023). "In our treatment paradigm, PUR did not increase the level of Gli1 mRNA, associated with canonical Shh signaling, giving additional credit to the potential safe use of PUR in stroke therapy." (PMID 25341035, 2014). "However, the lack of inflammation and an unchanged level of Gli1 mRNA on the contralateral side suggest that inflammation is not the only trigger of Shh signaling following stroke." (PMID 25341035, 2014).
thyroid cancer (6 papers, 2017 to 2023). "Therefore, additional studies of GANT61 and arsenic trioxide including association with GLI1 may facilitate a better understanding of the roles of hedgehog signaling pathway with respect to redifferentiation of RAI-refractory thyroid cancers." (PMID 35406554, 2022). "In summary, activating the SHH pathway through mutations in the RAS/BRAF/MEK pathway and the presence of paracrine factors in the interstitial space of thyroid cancer cells can enhance GLI1 expression and activity." (PMID 38313845, 2023). "In conclusion, GLI1 is associated with the initiation and progression of thyroid cancer, particularly in the context of RAIR-DTC, a subtype of thyroid cancer." (PMID 38313845, 2023). "In the present study, we demonstrated that inhibition of GLI1 transcription factor to restore endogenous NIS expression can improve RAI avidity in thyroid cancer-derived cells, which increases the I-131-mediated cytotoxic effect." (PMID 35406554, 2022). "Based on these results, TPC-1 and SW1736 thyroid cancer cells, which were highly expressed in the GLI1, were selected for subsequent experiments." (PMID 35406554, 2022). "Targeting GLI1 can be a potential strategy with redifferentiation for restoring RAI avidity in dedifferentiated thyroid cancers." (PMID 35406554, 2022). "Here, we investigated the role of GLI1 in the context of redifferentiation of RAI-refractory thyroid cancer." (PMID 35406554, 2022). "Studies have also verified the crosstalk between MAPK and GLI1 in thyroid cancers; in addition, an MEK inhibitor inhibits GLI1 activation, which suggests the possibility of a non-canonical mechanism of hedgehog signaling pathway activation." (PMID 35406554, 2022). "In the present study, knockdown of GLI1 alone decreased the colony-forming ability of thyroid cancer cells, which is consistent with the previous studies." (PMID 35406554, 2022). "Here we report that BMI1 and SOX2 were highly expressed in thyroid cancer and correlated with Gli1 levels." (PMID 33499351, 2021). "Clinicopathological analyses of thyroid tumor specimens by immunohistochemical (IHC) staining revealed that BMI1 and SOX2 were highly expressed in thyroid cancer and correlated with Gli1 expression." (PMID 33499351, 2021). "Our data indicate that all the thyroid cancer cells were positive for Gli1, Smo and Ptch expression, the latter being downregulated only in BCPAP cells." (PMID 29435119, 2018). "Suppression of the Shh pathway by Shh or Gli1 knockdown in KAT-18 thyroid cancer cell line leads to decreased size and number of thyrospheres, whereas Gli1 overexpression leads to increased number and size of thyrospheres." (PMID 29163356, 2017). "Moreover, a I-131-mediated cytotoxic effect was increased by pre-treatment with GLI1 siRNA and declined the colony-forming ability of thyroid cancer cells." (PMID 35406554, 2022). "Therefore, we examined the cellular localization of endogenous NIS by GLI1 knockdown in both thyroid cancer cells." (PMID 35406554, 2022). "Therefore, the GLI1 can be a potential therapeutic target of radioactive-iodine resistant thyroid cancers." (PMID 35406554, 2022). "Our findings demonstrated that inhibition of GLI1 could restore thyroid-specific proteins and transcription factors related to iodide-metabolizing machinery and promote redifferentiation in thyroid cancer cells." (PMID 35406554, 2022). "Therefore, we evaluated the potential use of the GLI1 transcription factor inhibition for promoting redifferentiation in thyroid cancer." (PMID 35406554, 2022). "Therefore, GLI1 inhibitor may potentially be added to other redifferentiation strategies to overcome therapeutic resistance or to obtain synergistic effects in RAI-refractory thyroid cancers." (PMID 35406554, 2022). "Next, we sought to observe an inverse relationship between the expression of GLI1 and NIS proteins in thyroid cancer cells." (PMID 35406554, 2022).
thyroid cancer (continued). "We evaluated GLI1 expression in several thyroid cancer cell lines and selected TPC-1 and SW1736 cell lines showing the high expression of GLI." (PMID 35406554, 2022). "In our study, knockdown of GLI1 increased endogenous NIS expression, especially the plasma membrane fraction in thyroid cancer cells." (PMID 35406554, 2022). "In this study, we investigated the role of GLI1 in the context of redifferentiation and improvement in the efficacy of RAI therapy for thyroid cancer." (PMID 35406554, 2022). "In the current study, we found that GLI1 knockdown can revert iodine non-avid thyroid cancers to iodine avid cancers by increasing expression of thyroid-specific proteins." (PMID 35406554, 2022). "Our ultimate goal was to induce conversion from dedifferentiation status to redifferentiation status with an increase in both thyroid-specific proteins and transcription factors by inhibiting the GLI1 transcription factor, thereby restoring RAI uptake in dedifferentiated thyroid cancers." (PMID 35406554, 2022). "Therefore, GLI1, as a novel target for inducing redifferentiation, is a potential alternative strategy to convert RAI-refractory thyroid cancers to RAI-sensitive thyroid cancers." (PMID 35406554, 2022). "Our recent study showed that GANT61, a Gli1 inhibitor, is able to control the growth of thyroid cancer stem cell-derived tumor but not effective to control the growth of bulk cell-derived tumors in a xenograft mouse model." (PMID 33966040, 2021). "However, the direct link between GLI1 and RAI uptake in thyroid cancers is not clear." (PMID 35406554, 2022).
chronic kidney disease (5 papers, 2017 to 2025). Impairment of the renal function secondary to chronic kidney damage persisting for three or more months. "Even the genetic ablation of adventitial Gli1+MSC-like cells in atherosclerotic mice affected by chronic kidney disease drastically decreases the level of vascular calcification." (PMID 28446225, 2017). "Chronic kidney disease (CKD) induces the failure of arteriovenous fistulas (AVFs) and promotes the differentiation of vascular adventitial GLI1-positive mesenchymal stem cells (GMCs)." (PMID 33001865, 2020). "Similarly, in chronic kidney disease (CKD)-related muscle injury, the natural compound Lobetyolin alleviates ferroptosis and muscle wasting by activating the Hedgehog-GLI1 signaling pathway, upregulating key ferroptosis suppressors." (PMID 41334559, 2025). "However, in the case of chronic kidney disease (CKD), Gli1+ cells differentiate into osteoblast-like cells to enhance vascular calcification." (PMID 40750730, 2025).
chronic myeloid leukemia (5 papers, 2015 to 2021). "HhP genes SHH, SMO, and GLI-1 are upregulated in chronic myeloid leukemia (CML) patients and are further elevated in blast crisis as compared to chronic-phase CML." (PMID 26483188, 2015). "It was documented that inhibition of the Shh pathway could silence the activity of GLI1/2/38,9 and thereby induced caspase-dependent apoptosis and growth inhibition in non-Hodgkin lymphoma cells and chronic myeloid leukemia cells." (PMID 31427566, 2019). "In chronic myeloid leukemia, LDE225 treatment inhibited cell growth with GLI1 downregulation." (PMID 33396427, 2020).
endometrial cancer (5 papers, 2010 to 2023). Primary or metastatic malignant neoplasm involving the endometrium (mucous membrane that lines the endometrial cavity). "Overexpression of Patched-1 has been reported in uterine and endometrial carcinoma, while Gli1 siRNA has been shown to suppress the expression of Patched-1 and induce apoptosis in Huh7 cells." (PMID 30521558, 2018). "We next analyzed the downstream effects of GSK3 inhibition with respect to Wnt/β-catenin and Hh crosstalk, as β-catenin interaction with Gli1 has previously been suggested to occur in endometrial carcinoma in which both factors cooperate to drive tumor growth." (PMID 25645196, 2015). "Ectopic expression of GLI1 induced β-catenin expression in the nuclei of endometrial cancer cell lines, and aberrant activation of this pathway may have a role in the development of endometrial cancer." (PMID 26633513, 2015). "Recently the link between Hedgehog and Wnt/β-catenin signaling has also been confirmed for atypical endometrial hyperplasia and endometrial cancer: in hyperplasia and in well differentiated endometrial cancers GLI1 overexpression overlaps with β-catenin nuclear immunoreactivity." (PMID 21317462, 2010).
fibrosis (5 papers, 2012 to 2025). the formation of excess fibrous connective tissue in an organ or tissue in a reparative or reactive process. "Multiple potential populations of myofibroblast progenitors have been associated with the progression of muscle fibrosis, among them FAPs as well as cells expressing specific markers such as a disintegrin and metalloprotease 1 (ADAM12) and glioma-associated oncogene 1 (Gli1)." (PMID 38289345, 2024). "Although the Smoothened inhibitor saridegib induced a modest reduction in spleen size and the degree of BM fibrosis, it did not reduce GLI1 mRNA or protein levels." (PMID 35595725, 2022).
gastric adenocarcinoma (5 papers, 2016 to 2021). "The aim of the present study was to identify the relation between Glioma-associated oncogene homolog 1 (Gli1) and stemness and determine its clinical significance in gastric adenocarcinoma (GA)." (PMID 32430068, 2020).
gastric tumor (5 papers, 2007 to 2023). "Unlike MALAT1 lncRNA expression, the fusion gene consisting of MALAT1 and glioma-associated oncogene 1 (GLI1; located at chromosome 12q13.3) is a diagnostic molecular marker for the rare gastric tumor plexiform fibromyxoma (PFM) and gastroblastoma." (PMID 37165307, 2023). "Kaplan–Meier curves and the log-rank test were used to assess the prognostic value of Gal-1 and Gli1 in gastric tumors." (PMID 27836001, 2016). "Gli-1 was also shown to potentiate the malignant phenotype via its antiapoptotic activity in gastric tumour cells." (PMID 17505514, 2007).
glomus tumor (5 papers, 2024 to 2025). A rare benign or malignant mesenchymal neoplasm arising from cells that resemble the modified smooth muscle cells of the glomus body. "Similar fusions including MALAT1::GLI1 and PTCH1::GLI1 were recently detected in tumors that resembled pericytic/glomus tumors or myoepithelial tumors." (PMID 38611033, 2024).
liposarcoma (5 papers, 2021 to 2025). A usually painless malignant tumor that arises from adipose tissue. "STAT6 expression has also been reported in dedifferentiated liposarcoma and GLI1-amplified tumors; hence, in cases with overlapping morphology and STAT6 immunoreactivity, additional molecular studies are needed to establish a definitive diagnosis." (PMID 34502329, 2021). "However, because the neoplasm is located in an atypical location for liposarcoma, the possibility of a neoplasm with GLI1 alteration, particularly GLI1 amplification, should also be considered." (PMID 38275873, 2024). "The previous results provided rationale that Gli2 may contribute a larger role in the state of dedifferentiation for liposarcoma tumors than Gli1." (PMID 37444470, 2023). "STAT6 nuclear expression is not exclusive to SFTs and has also been reported in dedifferentiated liposarcoma, glioma-associated oncogene homolog 1 (GLI1)-amplified tumor, Kaposi sarcoma and Hodgkin as well non-Hodgkin lymphomas." (PMID 34502329, 2021). "This means that when dealing with a large retroperitoneal tumor that expresses and/or amplifies MDM2, the initial consideration should be liposarcoma rather than a neoplasm with GLI1 alteration." (PMID 38275873, 2024). "This particularly applies to well-differentiated or dedifferentiated liposarcomas, which might not only benefit from MDM2 or CDK4 inhibitors, but also from anti-GLI1 therapies." (PMID 38275873, 2024). "Similarly, well-differentiated/dedifferentiated liposarcomas and other neoplasms with MDM2/CDK4 amplification may also exhibit coamplification of GLI1." (PMID 38275873, 2024). "Conversely, if a tumor is located in the head and neck or in an atypical liposarcoma location and shows MDM2 amplification, the possibility of a neoplasm with GLI1 alteration should be systematically ruled out." (PMID 38275873, 2024).
malignant rhabdoid tumors (5 papers, 2017 to 2025). "Loss of Snf5 leads to the activation of the Hh pathway, whereas its expression in the Gli1-dependent malignant rhabdoid tumors suppresses Gli1 activity and tumor growth." (PMID 30754706, 2019). "Conversely, re-expression of SNF5 in MRT (malignant rhabdoid tumor) cells inhibits GLI1." (PMID 40115023, 2025). "Additionally, in malignant rhabdoid tumors, the inactivation of SNF5, which directly interacts with GLI1 to suppress the expression of Hh target genes, including GLI1 and cyclin D, contributes to the activation of Hh signaling." (PMID 37394580, 2023).
myelofibrosis (5 papers, 2020 to 2024). A partial or complete replacement of the bone marrow stroma by fibrous tissue. "Prior studies have implicated Lepr+ or Gli1+ MSCs as the target of inflammatory signaling leading to myelofibrosis." (PMID 35439167, 2022). "On the one hand, Gli1+ cells can serve as precursors of fibroblasts and differentiate into fibroblasts through proliferation after vascular injury, and Gli1+ stromal cells also play a key role in myelofibrosis." (PMID 36711040, 2023). "Furthermore, in a thrombopoietin (TPO)-dependent mouse model of myelofibrosis, differentiation of Gli1+ MSCs toward myofibroblasts results in BM fibrosis; consistently, Gli1+ MSCs numbers are increased in patients with MPN." (PMID 32849521, 2020). "The findings of the mentioned study imply that the upregulation of GLI1 does not appear to be a characteristic of myelofibrosis etiopathogenesis." (PMID 39337361, 2024).
neuroendocrine tumors (5 papers, 2019 to 2025). "Thus, mutations in the MEN1 gene result in activation of GLI1 through increased binding of transcriptionally active GLI1 at its promoter, leading to the development of neuroendocrine tumors." (PMID 31244888, 2019). "Recent studies have highlighted the morphological similarities between well-differentiated neuroendocrine tumors and soft tissue sarcomas with GLI1 gene alterations described as “distinctive nested glomoid neoplasm”." (PMID 40248085, 2025). "SYT refers to the synaptotagmin family of proteins that can lead to aberrant activation of GLI1, which is particularly found in neuroendocrine tumors and glioblastomas." (PMID 39851545, 2025). "GLI1-rearranged enteric tumors may show a focal-to-patchy expression of synaptophysin and CD56, which may pose a diagnostic pitfall by mimicking neuroendocrine tumors." (PMID 39851545, 2025). "pNETs are known to have elevated GLI1 levels in the absence of menin, implying that inhibition of GLI1 could suppress formation of MEN1-related neuroendocrine tumors." (PMID 35747820, 2022).